SP1 (Sp1 transcription factor)
Diseases named in the same sentence as SP1 in open-access papers (continued):
Sharing a sentence is not in itself a finding about the gene and the disease.
Hyperglycemia (continued). "The hyperglycemia status enhances Sp1 binding at the MALAT1 promoter and elevated lncRNA MALAT1, enhances the binding of Sp1 at the Keap1 promoter, and activates its transcription." (PMID 38158644, 2024). "Previous studies have shown that there are two binding sites for SP1 in the ROBO4 promoter in HRECs, and that SP1 binding activity to ROBO4 was enhanced in hyperglycemia." (PMID 37430272, 2023). "Specificity protein 1 (SP1) has been reported to modulate ELF3 expression and influence hyperglycemia-induced COX2 and iNOS expressions in endothelial cells." (PMID 35607962, 2022). "Reduced thiamine availability and hyperglycemia impaired thiamine transport and THTR2/Sp1 expression." (PMID 33916491, 2021). "In general, our data indicate that SETD8 interacts with SP1 to coregulate ESE-1 expression, which is involved in hyperglycaemia-mediated endothelial apoptosis in HUVECs." (PMID 32185234, 2020). "Knockdown of HIF‐1α significantly inhibited SP1 and ROBO4, whereas SP1 down‐regulation abolished ROBO4 expression in RPE cells under hyperglycaemia/hypoxia." (PMID 31094072, 2019). "The suppressive effects of specific siRNAs on hyperglycaemia‐induced HIF‐1α, SP1, and ROBO4 up‐regulation were also observed by Western blotting." (PMID 31094072, 2019). "Hyperglycemia also activates HNF-1, Sp1, and HuR, leading to increased expression of SGLT1." (PMID 40932483, 2025). "Hyperglycemia and hyperinsulinemia upregulate SGLT1 by activating Sp1, HNF-1, and HuR." (PMID 40932483, 2025). "The metabolic disturbances and hyperglycemia in diabetic ischemic heart disease might alter the activity of kinases and transcription factors like DNA-PK, CDC2, MYC, SP1, and CREB1, exacerbating cardiac dysfunction." (PMID 39420368, 2024). "The effects of hyperglycemia on DNA methyltransferase 1, Tet methylcytosine dioxygenase 2 (TET2), 5-methylcytosine, 5-hydroxymethylcytosine, and the binding of TET2 and SP1 to the ROBO4 promoter, as well as the expression of ROBO4, zonula occludens 1 (ZO-1) and occludin were examined." (PMID 37430272, 2023). "Moreover, hyperglycemia reduced H3K4me1 and -me2 and increased the binding of Lysine-specific demethylase 1 (LSD1) and Sp1 at the Sod2 gene." (PMID 36732760, 2023). "Hyperglycemia promotes glucose use in the HBP, thus increasing the level of the end-product UDP-GlcNAc via the rate-limiting enzyme GFAT and increasing the rate of SP1 glycosylation with O-GlcNAc to promote SP1-induced transcription of ENTPD5." (PMID 36849424, 2023). "Furthermore, Sp1, a zinc finger transcription factor is also O-GlcNAcylated in response to high glucose concentrations and elevated Sp1 activity upon O-GlcNAcylation could play a role in hyperglycaemia-induced pro-fibrotic and pro-inflammatory factors involved in diabetic retinopathy." (PMID 35203353, 2022). "Additionally, HIF‐1α, SP1 and ROBO4 levels were elevated concomitantly in vivo in a model of DR and in vitro in RPE cells cultured under hyperglycaemia or hypoxia." (PMID 31094072, 2019). "Thus, HIF‐1α, SP1 and ROBO4 had important regulatory roles in RPE cells under hyperglycaemia or hypoxia." (PMID 31094072, 2019). "Additionally, HIF‐1α, SP1 and ROBO4 co‐expressed in the diabetic retina and in RPE cells under hyperglycaemia." (PMID 31094072, 2019). "Furthermore, SP1 binds to the VEGF-A promoter and upregulates VEGF-A expression during DR induced by hyperglycemia." (PMID 28706953, 2017). "The results showed that while hyperglycemia did not cause significant changes, PA and PA + G25 induced apoptosis-related cell death and significantly increased the expression of VEGFA, VEGFR2, HIF-α, and SP1." (PMID 42278667, 2026). "First, we found that HG-induced SP1 activation and SP1-directed dynein expression could be replicated in cells treated with compound C, a selective inhibitor of AMPK that mimics repressed AMPK in hyperglycemia." (PMID 38467599, 2024).
Hyperglycemia (continued). "In hyperglycemia and DKD conditions, the continual increase in UDP-GlcNAc inhibits GFAT expression via a negative feedback mechanism, resulting in a decrease in UDP-GlcNAc levels, inhibiting SP1 modification with O-GlcNAc and, therefore, downregulating ENTPD5 expression." (PMID 36849424, 2023). "MAPK p38 and ERK1/2 all contribute to the increased Sp1 activity that is induced by hyperglycemia; however, no study has reported whether the increased Sp1 activity induced by these pathways to mediate TSP-1 expression is the result of direct binding." (PMID 32626782, 2020).
lung adenocarcinoma (26 papers, 2012 to 2025). A carcinoma that arises from the lung and is characterized by the presence of malignant glandular epithelial cells. "Further analysis implicated the circSETDB1/miR-7/specificity protein 1 (Sp1) axis in the development and epithelial–mesenchymal transition (EMT) of lung adenocarcinoma." (PMID 36233088, 2022). "In our study, we first described the unfavorable prognostic value of nuclear ERα in early-stage lung adenocarcinoma using monoclonal antibody SP1, which has high sensitivity and affinity." (PMID 26318038, 2015). "In contrast, overexpression of Sp1 in highly invasive lung adenocarcinoma cells increases expression of E-cadherin and inhibits metastasis." (PMID 25099028, 2014). "This is in contrast with earlier reports where TAK1 has been shown to negatively regulate Sp1 activity in keratinocytes and lung adenocarcinoma cells." (PMID 24728340, 2014). "Sp1 and miR-182 were upregulated by more than 1.3-fold in 59.4% of the lung adenocarcinoma specimens when compared to expression in normal tissue." (PMID 24519909, 2014). "Additionally, research has demonstrated that SP1 can activate the expression of RGS20 through a super-enhancer to promote the progression of lung adenocarcinoma." (PMID 41304867, 2025). "It has been shown that SP1 is essential for tumor growth in lung adenocarcinoma; its expression is significantly increased during the neoplastic transformation stage and maintained during the 2nd and 3rd stages, but dramatically declines at the metastasis stage." (PMID 40843670, 2025). "More precisely, si-HOTAIR resulted in an increase in miR-326 expression, downregulation of Sp1 expression, and the subsequent restoration of sensitivity to cisplatin in lung adenocarcinoma (LAD) models, in both in vitro and in vivo lung adenocarcinoma (LAD) models." (PMID 38887279, 2024). "Moreover, the overexpression of miR-326 weakened cisplatin chemoresistance of lung adenocarcinoma cells by regulating specificity protein 1 (Sp1)." (PMID 35012553, 2022). "In stage I lung adenocarcinoma, nuclear ERα expression is observed in 17% of cases using monoclonal antibody SP1, which may become a potential target for anti-estrogen therapy." (PMID 26318038, 2015). "Moreover, Hsu reported that the proportion of low Sp1 expression in patients with stage IV lung adenocarcinoma was higher than that in patients with stages I and II of lung adenocarcinoma." (PMID 25099028, 2014). "The tumor suppressor LKB1 can inhibit the transcriptional activity of specificity protein 1 (SP1) by downregulating H4K8la and H4K16la, thereby inhibiting the transcriptional expression of TERT and inducing senescence in lung adenocarcinoma cells." (PMID 40589733, 2025). "In human lung adenocarcinoma cells, CLDN-2 knockdown decreases matrix metalloproteinase-9 activity and cell migration via suppression of nuclear Sp1." (PMID 36961882, 2023). "NG Ordonez reported that higher sensitivity can be obtained in distinguishing between malignant epithelial pleural mesothelioma and lung adenocarcinoma by immunostaining CEA and SP1." (PMID 34257529, 2021). "In the lung adenocarcinoma dataset, some mevalonate pathway genes displayed significant correlation with SREBP1 and SREBP2, but not SP1 (data not shown), suggesting possible coordinated regulation of such genes by NFY and SREBPs in cancer cells." (PMID 22211244, 2012).
acute myeloid leukemia (25 papers, 2012 to 2026). Acute myeloid leukemia (AML) is a group of neoplasms arising from precursor cells committed to the myeloid cell-line differentiation. "Homoharringtonine, approved for chronic myeloid leukemia, inhibits acute myeloid leukemia growth by targeting the specificity protein 1 (SP1)/TET1 axis and reducing 5hmC levels." (PMID 40520993, 2025). "After normal tissues from TCGA and GTEx databases were matched, higher AP1G1 and SP1 gene expression levels were observed in acute myeloid leukemia (LAML) (p < 0.05) compared to normal tissues." (PMID 39056681, 2024). "Curcumin inhibits DNA methylation by covalently blocking the catalytic thiolate of DNMT1 and reducing the expression of tumor suppressor gene Sp1 Transcription Factor (Sp1) and Transcription factor p65 (p65) in acute myeloid leukemia (AML) cell lines in vitro and in vivo." (PMID 35774614, 2022). "Previous studies in acute myeloid leukemia (AML) cells found elevated m6A levels on SP1 transcript, which promoted its stability and translation." (PMID 39902961, 2025). "There was a regulatory Sp1/NFkB/HDAC/miR-29b network to control oncogene expression in acute myeloid leukemia (AML)." (PMID 22359598, 2012). "For instance, the Wnt/β-catenin pathway is regulated by the miR-29b/Sp1/FUT4 pathway, which controls acute myeloid leukemia (AML)." (PMID 38343056, 2024). "Other proteins of this pathway that interact with SP1 include FLT3 which is important for the normal development and the immune system and is a drug target for acute myeloid leukemia (AML).68." (PMID 38410465, 2024). "In acute myeloid leukemia (AML), METTL3 promotes oncogenes SP1 translation by decreasing ribosome stalling." (PMID 34150845, 2021). "Taken together, our data supported that constitutive activation of the ERK/MSK/Sp1 axis (as shown by phosphorylation of the pathway components) was required for over-expression of survivin in CD34+ AML patients, and finally permitting the evolution to the “Seed cell” in acute myeloid leukemia." (PMID 25890196, 2015). "For instance, in acute myeloid leukemia (AML), the transcriptional complex NF-κB/Sp1 can interact with HDAC1 and HDAC3 to form the NF-κB/Sp1/HDAC complex on miR-29b enhancer, which resulted in the silencing of miR-29b." (PMID 24261995, 2013). "SP1 modulated the expression of DNMT1 gene through mechanisms such as protein abundance, post‐translational modifications or interaction with other transcription factors in human acute myeloid leukaemia cells." (PMID 28840963, 2018). "Several previous studies suggested that Sp1 may regulate the expression and function of COX2 in ovarian epithelial cancer and of acute myeloid leukemia." (PMID 27057636, 2016). "These include many transcription factor binding sites that are commonly functional in myeloid promoters including PU.1, SP1, myeloid zinc finger protein (MZF1), nuclear factor kappa B (NF-κB) or p50, octamer factor binding sequences (OCT) and acute myelogenous leukemia (AML1)." (PMID 23840844, 2013). "Bortezomib decreases Sp1 protein levels, disrupts the interaction of Sp1 with NF-kappaB, and prevents binding of the Sp1/NF-kappaB complex to the DNMT1 gene promoter for repression in acute myeloid leukemia." (PMID 23148884, 2012). "For instance, in acute myeloid leukemia (AML), increased m6 A levels on SP1, MYB, MYC, BCL2, and PTEN enhance the stability and translation of their corresponding mRNAs, contributing to the onset and progression of AML." (PMID 40382536, 2025). "It was found that METTL3 and METTL14 (writers) served an oncogenic role in acute myeloid leukemia (AML) in an m6A manner by promoting the translation of MYC, MYB, BCL2, SP1, and PTEN." (PMID 36281789, 2022). "This is in a sharp contrast to the transcript 1 promoter that was reported to be activated by Sp1 in HEK 293, HeLa, and Acute Myeloid Leukemia (AML) cells HL-60 and HEL." (PMID 27775603, 2016).
atherosclerosis (25 papers, 2015 to 2025). A disease characterized by the build-up of fatty material and calcium deposition in the arterial wall resulting in partial or complete occlusion of the arterial lumen. "SP1 is linked to pro-fibrosis, an inflammation in many diseases such as muscular dystrophy and atherosclerosis." (PMID 40677917, 2025). "The increase in pro-fibrotic SP1 in macrophages of the high-CRP group is likely associated with increased fibrosis related to atherosclerosis." (PMID 39737187, 2024). "This suggests that Sp1 phosphorylation is more closely associated with the development of atherosclerosis than with the maintenance of cholesterol stability." (PMID 39252788, 2024). "The top transcriptional factor motif that showed rapamycin-mediated hypermethylation was SP1, which is involved in several aging-associated diseases including cancer, hypertension, atherosclerosis, Alzheimer’s, and Huntington diseases." (PMID 34482522, 2021). "Dwyer et al8 reported that the observed association between ALOX5 SP1 tandem variation and atherosclerosis was modified by dietary intakes of AA, EPA, and DHA." (PMID 27025886, 2016). "Studies have shown that SP1 protects cardiomyocytes from inflammatory damage in atherosclerosis by inhibiting the NF-κB signaling pathway." (PMID 40661956, 2025). "Overall, these findings indicate that the effects of Sp1 phosphorylation on the contraction, proliferation, and migration of VSMCs during various stages of atherosclerosis are bidirectional." (PMID 39252788, 2024). "Phosphorylated Sp1 can upregulate eNOS expression, thereby maintaining vascular integrity and preventing atherosclerosis." (PMID 39252788, 2024). "This miRNA inhibits specificity protein 1 (SP1), activating NF-kB P65 signaling and promoting the release of ICAM-1 and VCAM-1, thus causing the progression of atherosclerosis." (PMID 39767590, 2024). "FOS, ESR1, MAPK8, and SP1 are important targets for anti-aging, anti-atherosclerosis, and anti-fatigue." (PMID 39334763, 2024). "A significant correlation exists between Sp1 phosphorylation and the development of atherosclerosis." (PMID 39252788, 2024). "EPC-EVs transfer miR-199a-3p to inhibit specific protein 1 (SP1), thereby suppressing ferroptosis in ECs and delaying the occurrence of atherosclerosis." (PMID 38840175, 2024). "Collectively, our findings demonstrate that miR‐4532 in exosomes secreted by macrophages can be taken up by vascular endothelial cells, where it regulates SP1 expression and activates the NF‐κB P65, which promotes atherosclerosis." (PMID 36071548, 2022). "Collectively, these results demonstrated the positive regulation of Sp1 on miR‐195‐3p expression in atherosclerosis." (PMID 34592792, 2021). "Increased β-1,4-GalT-V activity and elevated LacCer levels have been detected in renal tubular cells from patients with the homozygous familial hypercholesterolemia, suggesting a role for Sp1 in atherosclerosis by modulating β-1,4-GalT-V expression and LacCer production." (PMID 40869407, 2025). "Consequently, therapeutic strategies targeting phosphorylated Sp1 in the treatment of atherosclerosis must carefully weigh the potential benefits against the associated risks, suggesting the necessity of identifying an optimal balance." (PMID 39252788, 2024). "In fact, previous studies have reported a role for Sp1 in experimental atherosclerosis." (PMID 38537695, 2024). "Therefore, targeting the phosphorylation of Sp1 represents a promising therapeutic strategy for mitigating atherosclerosis." (PMID 39252788, 2024). "Interestingly, miR-636 was identified to promote atherosclerosis development via SP1 and lysine degradation." (PMID 36991398, 2023). "Li Lin showed that inhibiting SP1 could repress ferroptosis of endothelial cells and retard the occurrence of atherosclerosis." (PMID 36275721, 2022).
atherosclerosis (continued). "For example, SP1 is a key regulator of mTORC1/P70S6K/S6 signaling pathway and is involved in several aging-associated diseases including cancer, hypertension, atherosclerosis, Alzheimer’s, and Huntington diseases." (PMID 34591235, 2022). "Further, exosomal miR‐4532 transferred from macrophages to HUVECs and targeting specificity protein 1 (SP1) may be a novel therapeutic target in patients with atherosclerosis." (PMID 36071548, 2022). "In addition, several reports showed a role for Sp1 in atherosclerosis." (PMID 38537695, 2024). "Atherosclerosis (AS) is a common age-related disease, and a research found that circPTPRA was upregulated in serum samples of AS patients, which promoted cell proliferation and inhibited cell apoptosis through repressing miR-636 and upregulating SP1 signaling axis." (PMID 34262589, 2021). "High glucose or glucosamine can affect cardiovascular function by regulating Sp1 to increase the expression of plasminogen activator inhibitor-1 (PAI-1) and TGFβ, both of which are involved in atherosclerosis." (PMID 39252788, 2024). "The molecular mechanism analysis revealed that the active components of WGP have a positive influence on the four potentially important therapeutic targets of aging, atherosclerosis, or fatigue (i.e., FOS, ESR1, MAPK8, and SP1)." (PMID 39334763, 2024). "For example, circPTPRA is upregulated in serum of patients with atherosclerosis (As) promotes VSMC proliferation by sponging miR-636 and upregulating the transcription factor SP1." (PMID 37498354, 2023). "Our data reveal links among SP1, miR-320a, SRF and miR-1/miR-133a in endothelial dysfunction in atherosclerosis." (PMID 25728840, 2015). "In addition, butyrate could improve atherosclerosis through the upregulation of ABCA1 expression and cholesterol efflux in macrophages through the Sp1 pathway." (PMID 33312718, 2020). "The top three WGP ingredients (quercetin, EGCG, and kaempferol) could bind stably to the top four core genes of aging, atherosclerosis, and fatigue (FOS, ESR1, MAPK8, and SP1), except that EGCG could not dock successfully with SP1." (PMID 39334763, 2024).